CT45A6 (cancer/testis antigen family 45 member A6)
Synonyms: CT45-6; CT45.6
Tractability: PROTAC: ubiquitination databases record sites on it.
Gene: Protein-coding gene on chromosome X (135,794,685 to 135,802,787, reverse strand). Ensembl gene ENSG00000278289.
Subcellular location (Human Protein Atlas): Nucleoli; Nucleoplasm
Homologues: Orthologues: rat Ct45a9 (29% identical), mouse Ct45a (28% identical), Caenorhabditis elegans ints-6 (17% identical), Drosophila melanogaster IntS6 (16% identical). Paralogues in human: CT45A5 (100% identical), CT45A7 (100% identical), CT45A3 (99% identical), CT45A1 (99% identical), CT45A2 (98% identical), CT45A8 (98% identical), CT45A9 (98% identical), CT45A10 (95% identical), SAGE1 (35% identical), INTS6L (31% identical), INTS6 (26% identical).
Diseases named in the same sentence as CT45A6 in open-access papers:
CT45A6 is named in the same sentence as 2 diseases in open-access papers, as found by Europe PMC text mining. Sharing a sentence is not in itself a finding about the gene and the disease. The quoted sentences say what the papers report.
cancer (2 papers, 2012 to 2019). A tumor composed of atypical neoplastic, often pleomorphic cells that invade other tissues. "Examples of biclusters from this category include the biclusters consisting of genes from the Cancer-Testis antigens family—MAGEA2, MAGEA3, MAGEA6, MAGEA10, CSAG1, CSAG2, CSAG3 (Xq28)/CT45A3, CT45A5, CT45A6 (Xq26.3)." (PMID 31216036, 2019).
tumor (1 paper, 2019). "Among them were known cancer/testis antigen genes (PNMA5, SPATA22, ROR1, and CT45A6) and some new candidates (PAX2, HES4, PEG10, NTN4, PDE10A, and POSTN), these genes could be useful tumor markers and potential therapeutic targets." (PMID 30922328, 2019).